CEACAMP8 (CEA cell adhesion molecule pseudogene 8)
Synonyms: formerly CGM15
Gene: Unprocessed pseudogene on chromosome 19 (43,035,869 to 43,041,248, reverse strand). Ensembl gene ENSG00000236932.
Diseases named in the same sentence as CEACAMP8 in open-access papers:
CEACAMP8 is named in the same sentence as 2 diseases in open-access papers, as found by Europe PMC text mining. Sharing a sentence is not in itself a finding about the gene and the disease. The quoted sentences say what the papers report.
preeclampsia (2 papers, 2013 to 2017). Preeclampsia is a hypertensive disorder of pregnancy that is characterized by new-onset hypertension with proteinuria presenting after 20 weeks of gestation, and depending on mild or severe forms may initially present with severe headache, visual disturbances, and hyperreflexia. "Misregulation of LOC391533, LOC284100, and CEACAMP8 might contribute to the mechanism underlying preeclampsia." (PMID 24312300, 2013). "LOC284100 and CEACAMP8 are associated with LPL mRNA expression, while hyperlipidemia is one common complication of preeclampsia." (PMID 24312300, 2013). "LOC391533, LOC284100, and CEACAMP8 were evaluated using qPCR in 40 preeclampsia placentas and 40 controls." (PMID 24312300, 2013). "According to the CNC network and the GO analysis of LncRNA/mRNA expression profiling, we examined the expression of three lncRNAs (LOC391533, LOC284100, CEACAMP8) in 40 preeclampsia placenta tissues and 40-matched control placenta tissues using qPCR (p<0.05 for each lncRNAs)." (PMID 24312300, 2013).
CEACAMP8 also shares sentences with these, for which no sentence is quoted: hyperlipidemia (1 paper).